SNORD39 (Small nucleolar RNA SNORD55/SNORD39 )
Synonyms: LOC124900178
Gene: Small nucleolar RNA gene on chromosome 4 (158,909,373 to 158,909,450, reverse strand). Ensembl gene ENSG00000274535.
Gene Ontology:
Biological process: RNA processing
Cellular component: nucleolus
Homologues: Orthologues: chimpanzee SNORD39 (100% identical), macaque SNORD39 (88% identical), guinea pig SNORD39 (62% identical), dog SNORD39 (59% identical), tropical clawed frog SNORD39 (51% identical), tropical clawed frog SNORD39 (46% identical). Paralogues in human: SNORD55 (71% identical), SNORD39 (59% identical), SNORD39 (54% identical).